PRAME-AS (PRAME antisense RNA)
Synonyms: LL22NC03-63E9.3
Gene: Long non-coding RNA gene on chromosome 22 (22,559,343 to 22,566,602, forward strand). Ensembl gene ENSG00000220891.
Gene Ontology:
Biological process: miRNA-mediated post-transcriptional gene silencing
Diseases named in the same sentence as PRAME-AS in open-access papers:
PRAME-AS is named in the same sentence as 2 diseases in open-access papers, as found by Europe PMC text mining. Sharing a sentence is not in itself a finding about the gene and the disease.
PRAME-AS shares sentences with these, for which no sentence is quoted: cancer (1 paper); tumor (1).